CEROX1 (cytoplasmic endogenous regulator of oxidative phosphorylation 1)
Gene: Long non-coding RNA gene on chromosome 16 (974,131 to 981,675, reverse strand). Ensembl gene ENSG00000260807.
Diseases named in the same sentence as CEROX1 in open-access papers:
CEROX1 is named in the same sentence as 9 diseases in open-access papers, as found by Europe PMC text mining. Sharing a sentence is not in itself a finding about the gene and the disease. The quoted sentences say what the papers report.
neuroblastoma (3 papers, 2019 to 2023). Neuroblastoma (NB) is the most common solid, extracranial childhood tumor. "The lncRNA cytoplasmic endogenous regulator of oxidative phosphorylation 1 (Cerox1) sponges miR-488-3p and elevates the expression of several subunits of complex I in mouse neuroblastoma cells." (PMID 33123488, 2020). "In mouse neuroblastoma (N2A) cells the most highly expressed Cerox1 transcript is enriched in the cytoplasmic fraction with a short half-life of 36 ± 16 mins and is mainly associated with the ribosome-free fraction." (PMID 31045494, 2019). "Another lncRNA, cytoplasmic endogenous regulator of oxidative phosphorylation 1 (Cerox1), binds to and inhibits miR-488-3p to enhance the expression of multiple ETC complex I subunits and mitochondrial respiration in N2A neuroblastoma cells." (PMID 37298366, 2023).
glioblastoma (1 paper, 2022). The most malignant astrocytic tumor (WHO grade IV). "Several lncRNAs were associated with GBM molecular subtype; CEROX1 and novel lncRNA ENSG00000262223 expression was upregulated in proneural as compared to mesenchymal glioblastoma subtype (data not shown)." (PMID 35361860, 2022).
glioma (1 paper, 2019). A benign or malignant brain and spinal cord tumor that arises from glial cells (astrocytes, oligodendrocytes, ependymal cells). "A summary-data-based Mendelian randomization analysis that uses rs3809674 as an instrumental variable, predicts an effect of CEROX1 gene expression on glioma risk." (PMID 31045494, 2019).
Huntington disease (1 paper, 2019). Huntington disease (HD) is a rare neurodegenerative disorder of the central nervous system characterized by unwanted choreatic movements, behavioral and psychiatric disturbances and dementia. "We note that the highest expression of CEROX1 occurs primarily in the basal ganglia regions of which are specifically vulnerable to the progressive neurological disorders Parkinson’s (substantia nigra pars compacta) and Huntington’s diseases (striatum: caudate and putamen)." (PMID 31045494, 2019).
low grade glioma (1 paper, 2022). A grade I or grade II glioma arising from the central nervous system. "Gene expression-based survival analysis showed that six from seven detected highly m6A modified lncRNAs (PVT1, SLCO4A1, HRAT92, AGAP2-AS1, CEROX1 and ENSG00000262223 had an impact on the prognosis of low-grade glioma (LGG) and GBM (FDR adj." (PMID 35361860, 2022).
memory impairment (1 paper, 2025). "Based on the changes in expression, along with its evolutionary conservation and lack of protein coding potential we chose to characterize the role of Cerox1 in memory impairment caused by sleep deprivation." (PMID 41255986, 2025).
viral meningitis (1 paper, 2024). Inflammation of the membranes surrounding the brain and spinal cord due to a viral infection. "In viral meningitis specific co-expression networks, a total of 9 significantly upregulated lncRNAs (AC243830.1, AC092111.1, CEROX1, AC246817.2, FAM66C, LINC01535, LINC02848, CHKB-DT, and C18orf15) were identified." (PMID 38347610, 2024).
cancer (1 paper, 2019). A tumor composed of atypical neoplastic, often pleomorphic cells that invade other tissues. "This microRNA shares with Cerox1 an early eutherian origin and elevated expression in brain samples, and it previously was shown to alter mitochondrial dynamics in cancer cells." (PMID 31045494, 2019).
CEROX1 also shares sentences with these, for which no sentence is quoted: Parkinson’s (1 paper).